CXCR2 (C-X-C motif chemokine receptor 2)
Diseases named in the same sentence as CXCR2 in open-access papers (continued):
Sharing a sentence is not in itself a finding about the gene and the disease.
colitis (continued). "Studies have also shown that the blockage of CXCR2 in neutrophils by a selective inhibitor could significantly alleviate the symptoms of DSS-induced colitis in mice and could suppress the production of proinflammatory cytokines." (PMID 34306038, 2021). "Genetic depletion of Cxcr2 (Cxcr2 knockout mice) diminished massive infiltration of granulocytic-MDSC into the tumors and retained them in their circulatory system, reducing chronic colonic inflammation and colitis-associated tumorigenesis." (PMID 27136535, 2016). "Similarly, blocking CXCR2 with antibodies or with antagonists dampens colitis, as knockdown or blockage of some other CCR and CXC receptors." (PMID 27999328, 2016). "CXCR2 knockout mice are protected against DSS-colitis-induced acute kidney injury and inflammation." (PMID 26648169, 2015). "After 7 days of induced colitis, upregulation of the expression of 22 genes (Ccl2, Ccl3, Ccl4, Ccl5, Ccl6, Ccl7, Ccl12, Ccl17, Cxcl1, Cxcl2, Cxcl6, Cxcl9, Cxcl11, Ccr1, Ccr2, Ccr3, Ccr5, Ccr8, Cxcr2, Csf3, Osm, and Spp1) was observed in the CβG− group compared to the HβG- control group." (PMID 35163326, 2022). "In a mouse model of colitis-associated CRC, the levels of CXCR2 ligands were significantly elevated in inflamed colonic mucosa and tumors compared with in adjacent normal mucosa, and CXCR2+ MDSC accelerated tumor growth by inhibiting CD8+ T cell cytotoxicity activity." (PMID 27136535, 2016). "The expression of CXCR2 and its ligands CXCL1 and CXCL5 was markedly lower in the PAI-1 KO group than in the WT (colitis) group following DSS treatment." (PMID 37151884, 2023). "Our data suggest that the involvement of PAI-1 in the pathogenesis of colitis mainly affects CXCL1/CXCL5 and their receptor CXCR2, which are important for neutrophil recruitment and tissue injury." (PMID 37151884, 2023). "Genetic knockout of PAI-1 or pharmaceutical blockade of CXCR2 has comparable protective effects, preventing mice from developing DSS-induced colitis." (PMID 37151884, 2023). "In the colitis group, the expression of CXCL1 was lower and the expression of CCL5 and CXCR2 was higher compared to the control group." (PMID 35163326, 2022). "Upregulated mucosal expression of numerous chemokines and their counter receptors including CXCL8 (IL-8)/CXCR2, CXCL9,10,11/CXCR3, CCL25/CCR9, CCL19,21/CCR7, and CCL20/CCR6 is evident in active IBD and in models of colitis." (PMID 22162719, 2012). "It has been shown that selective blockade of IL-1R, CXCR2, CXCL1/KC, MCP-1, MIP-2, TNF-α and IL-6 significantly decreases severity of colitis and neutrophil/macrophage migration." (PMID 22073270, 2011). "Knockout of CXCR2, which is the receptor of CXCL2 could protect mice against DSS-colitis-induced AKI and inflammation, indicating the therapeutic value of CXCL2 in AKI." (PMID 38753279, 2024). "The gene expression of Ccr2, Ccr5, and Cxcr2 was increased in colitis rats fed with feed without beta-glucan (βG−) compared to the control group (HβG−) at both time points, whereas Ccr1 gene expression was increased only after 3 days of TNBS administration." (PMID 35163326, 2022). "More importantly, mesalazine treatment reversed the suppressive effect of immune responsive genes, including chemokine (C–X–C motif) ligand (CXCL3), chemokine (C–C motif) ligand (CCL11 and CCL21), chemokine receptor (CXCR2), and colony-stimulating factor (CSF3) in the DSS-induced colitis model." (PMID 34456974, 2021). "Accordingly, we observed that the expression levels of genes encoding chemokines (Ccl3, Ccl4, and Ccl6), chemokine receptors (Ccr1, Ccr5, Cxcr2, Cxcl1, Cxcl2, and Cxcl13), and inflammatory factors (Mpo, Il-1β, and Il12) were increased in mice with DSS-induced colitis." (PMID 34795650, 2021). "The depletion or blocking of CXCR2 was protective against acute and chronic DSS colitis." (PMID 26497661, 2015). "However, the inhibition of neutrophil migration by a CXCR2 antagonist did not alleviate DSS-induced colitis in ERdj5-KO mice." (PMID 36759578, 2023).
colitis (continued). "The results showed that acute and pre-remission stages of colitis were characterized by the increased gene expression of seven chemokines and four chemokine receptors in the colon wall as well as disrupted protein expression of CXCL1, CCL5, CXCR2, CCR5, and OPN in the mucosa." (PMID 35163326, 2022). "However, the CXCR2 inhibitor SB225002 did not affect the diseases of colitis alone." (PMID 36951545, 2023).
atherosclerosis (37 papers, 2008 to 2025). A disease characterized by the build-up of fatty material and calcium deposition in the arterial wall resulting in partial or complete occlusion of the arterial lumen. "The receptor for MIF, CXCR2, has also been implicated in atherosclerosis as CXCR2 deficiency results in reduced lesion size and lesional macrophage content." (PMID 26175090, 2015). "Cxcl1 and Cxcr2 are also implicated in mobilization of monocytes, in models of atherosclerosis and is Cxcr2 expressed by CNS- and retinal-derived monocytes." (PMID 25595590, 2015). "Previous studies demonstrated that CXCR2 could promote the recruitment of neutrophils in hyperlipidemic mice and is associated with early atherosclerosis." (PMID 41446394, 2025). "However, increased CXCR2 expression on monocytes/macrophages has already been associated with atherosclerosis and found on PBMC and within atherosclerotic plaques in humans and murine." (PMID 38533504, 2024). "CXCR2 has also been found to be associated with the progression of atherosclerosis." (PMID 35795659, 2022). "Its expression is proatherogenic as CXCR2 deficiency reduces the progression of advanced atherosclerosis in mice, and it may have a role in retaining macrophages in the lesions." (PMID 18579408, 2008). "Like the other receptors already discussed, CXCR1 and CXCR2 play a crucial role in the development of several CVDs, such as atherosclerosis, ischemia, cardiac remodeling, and hypertension." (PMID 40859641, 2025). "Our findings are consistent with prior studies demonstrating that blockade of the CXCL-8/CXCR2 axis limits monocyte transmigration and lesion development in early atherosclerosis." (PMID 41280941, 2025). "CXCL1/CXCR2 signaling are widely studied in cardiovascular diseases, including cardiac hypertrophy, hypertension, aneurysm, and atherosclerosis." (PMID 38601164, 2024). "As a 7-transmembrane G protein-coupled receptor (7GPCR), CXCR2 is responsible for chemotaxis in immune responses and is upregulated in inflammatory conditions, such as RA, psoriasis, and atherosclerosis." (PMID 38515019, 2024). "IL-8, through its interaction with CXCR2, triggers to the formation of neutrophil extracellular traps that aggravate the progression of atherosclerosis in vivo, and CXCR2 was identified as a common hub gene for peripheral arterial disease (PAD)." (PMID 38528533, 2024). "CXCR2 depletion by using CXCR2 blocking antibody inhibited NETs formation and alleviated atherosclerosis progression in Apoe−/− mice fed with WD for 12 weeks." (PMID 34359859, 2021). "As the CD74/CXCR2 complex is implicated in MIF-mediated chemotaxis, these receptors are associated with atherosclerosis." (PMID 26175090, 2015). "The receptor for CXCL1 CXCR2 is present on myeloid cells like neutrophils and monocyte/macrophages, which are directly involved in all aspects of atherosclerosis." (PMID 24879339, 2014). "The chemokine receptors CCR2 and CXCR2 were expressed in the arterial endothelial cells of human atherosclerosis, in addition to their expected expression in the U937 cells, which we have confirmed." (PMID 18579408, 2008). "Recently, the cytokine MIF (macrophage migration inhibition factor) has been found to have a role in leukocyte recruitment in atherosclerosis by signalling through CXCR2 and CXCR4." (PMID 18579408, 2008). "Studies have shown that CXCR2 plays an important role in promoting the migration and recruitment of monocytes/macrophages to damaged heart and arterial walls and promoting pathological myocardial remodeling, acute myocardial infarction and atherosclerosis." (PMID 40183084, 2025). "MIF-CD74 works with CXCR2 to act as a chemotactic agent, promoting atherosclerosis progression." (PMID 36712241, 2022).
atherosclerosis (continued). "MIF binds to the chemokines CXCR2 and CXCR4, recruits leukocytes, and accelerates the process of atherosclerosis." (PMID 38625586, 2024). "MIF has a chemokine-like function that activates CXCR2 and CXCR4, and thus can recruit monocytes and T lymphocytes to promote atherosclerosis." (PMID 36712241, 2022). "IL-8 interacts with CXCR2 on neutrophils, leading to the formation of neutrophil extracellular traps via Src and ERK and p38 MAPK signaling, aggravating the progression of atherosclerosis in vivo." (PMID 35795659, 2022). "The two inflammatory receptors CXCR2 and CXCR3 have also been widely involved in the pathogenesis of atherosclerosis." (PMID 34440065, 2021). "Numerous studies have demonstrated the importance of the CCR2/CCL2 (MCP-1), CX3CR1/CX3CL1 (fractalkine), CXCR2/CXCL1, and CCR5/CCL2/CCL5 interactions in the progression of experimental atherosclerosis." (PMID 31195722, 2019). "During early atherosclerosis, CXCL1/GRO-α immobilized on the surface of endothelial cells via heparin proteoglycans induces the firm adhesion of rolling monocytes expressing CXCR2." (PMID 22807925, 2012). "CXCL8 interacted with its receptor CXCR2 on neutrophils, leading to the formation of NETs via Src and extracellular signal-regulated kinase (ERK) and p38 mitogen-activated protein kinases (MAPK) signaling to aggravate atherosclerosis progression in vivo." (PMID 33503867, 2021). "The ubiquitously expressed chemokine, macrophage migration inhibition factor (MIF) was demonstrated as a noncognate ligand of CXCR4 (and CXCR2), shown to facilitate leukocyte recruitment during inflammatory diseases such as atherosclerosis." (PMID 25283599, 2015). "In the context of atherosclerosis, interference with MIF binding to both CXCR2 and CXCR4 by using a MIF blocking antibody interfered with MIF’s pro-atherosclerotic functions, while it would leave the protective homeostatic functions of the CXCL12-CXCR4 axis preserved." (PMID 23720662, 2013). "MIF not only interacts with CD74, but also engages in high affinity interactions with the chemokine receptors CXCR2 and CXCR4 to drive inflammatory leukocyte recruitment processes and may mediate the inflammatory pathogenesis of experimental atherosclerosis." (PMID 22506003, 2012). "We think that this could be because in conditions of extent atherosclerosis and systemic vascular remodeling, there can be an increased migration of VEGFR2hi-neutrophils into the tissue (mediated by both VEGFR and CXCR2), which leads to a decrease in their number in the systemic circulation." (PMID 35518568, 2022). "Some CXCR2- and CCR2-specific antagonists (i.e., reparixin and MLN1202) have already been tested as therapeutic drugs in clinical trials, like MLN1202, which is a CCR2-blocking monoclonal antibody shown to reduce high-sensitivity CRP as surrogate parameter for atherosclerosis." (PMID 22807925, 2012). "Furthermore, blockade of MIF (macrophage migration inhibitory factor) but not of canonical ligands of CXCR2 or CXCR4 in mice with advanced atherosclerosis led to plaque regression and reduced monocyte and T-cell content in plaques." (PMID 21188276, 2010).
COVID-19 (36 papers, 2020 to 2025). A disease caused by infection with severe acute respiratory syndrome coronavirus 2. "In the dominant inheritance model, the CXCR2 - (CT+CC) genotype was found to be significantly associated with susceptibility to COVID-19 (OR = 2.09, 95% CI= 1.1626 to 3.5441, RR= 1.45 and p = 0.012)." (PMID 38544825, 2024). "In the codominant model, a statistically significant association was noted between the CXCR2 rs2230054 CT genotype and susceptibility to COVID-19 (OR 2.0, 95% CI = 1.184 to 3.681, RR = 1.41 and p = 0.011)." (PMID 38544825, 2024). "The polymorphisms in TNFα -308 G>A (rs1800629), IL-8 -251T>A (rs4073), IL-10 (-1082 G>A), rs1800896 and CXCR2 +785 C>T (rs2230054) are associated with the risk of susceptibility to COVID-19 and with mortality in COVID-19 patients." (PMID 38544825, 2024). "In this study, we aimed to find out the association of genetic polymorphisms in TNF-α, IL-8, IL-10 and CXCR-2 genes with susceptibility to and mortality of COVID-19." (PMID 38544825, 2024). "Our investigations revealed that the frequency of the CXCR2 rs2230054 C>T CT genotype is higher in COVID-19 patients, and the risk of COVID-19 infection is higher in individuals with the CXCR2 rs2230054 C>T CT and (CT+CC) genotypes." (PMID 38544825, 2024). "Severe COVID-19 is associated with alterations to the neutrophil compartment with circulating hyperactive immature neutrophils and a maintenance of CXCR2 expression." (PMID 36622345, 2023). "Because both moderate and severe COVID-19-associated neutrophils are immature, it is unlikely that a difference in maturation state between these groups explains the divergent expression of CXCR2." (PMID 36622345, 2023). "Also, increased expression of CXC chemokine receptor 2 (CXCR2) has been found to be associated with increased severity and mortality in COVID-19 patients." (PMID 38544825, 2024). "TNF-α-GA and AA genotypes and A allele, IL-8 TA and AA genotypes and A allele and CXCR-2 CC and CT genotypes have significant associations with mortality risk in COVID-19 patients, while GA and GG genotypes of the IL-10 are shown to confer significant protection against mortality from COVID-19." (PMID 38544825, 2024). "Maintenance of neutrophil CXCR2 expression in severe COVID-19 may promote lung trafficking and associated tissue damage and perfusion defects." (PMID 36622345, 2023). "Since severe COVID-19 is associated with increased serum IL-8 concentrations, we hypothesize that this decreased CXCR2 expression could be a distal effect of excessive IL-8 being released by myeloid cells already recruited to the lungs, possibly suppressing further migration." (PMID 39253969, 2024). "In fact, CCRL2 and CXCR2 expression levels were upregulated in circulating neutrophils from COVID-19 patients." (PMID 39811276, 2025). "Similar patterns have been observed in human studies of COVID-19, where elevated CXCR2+ neutrophils in the blood correlate with increased neutrophil infiltration in the lungs and are associated with worse clinical outcomes." (PMID 40475786, 2025). "Navarixin (MK-7123/SCH 527123), and other CXCR2 inhibitors, have been proposed as a pharmacological intervention to treat COVID-19." (PMID 38596679, 2024). "Frequencies of TNF-α rs1800629 GA, AA, IL-8 rs4073 TA, AA, IL-10 (-1082 G>A), rs1800896 GA and GG, and CXCR2 rs2230054 CT genotypes were significantly higher in COVID-19 patients compared to the control group (p < 0.05)." (PMID 38544825, 2024). "We and others have shown that CXCR2, the IL-8 receptor, is downregulated on neutrophils from patients with COVID-19." (PMID 39253969, 2024). "The mild COVID-19 group were overrepresented in population 0 (CD16+CD10+CD62L+CXCR2+CXCR4+) and population 7 (CD16+CD10+CD63+PD-L1hiLOX-1+CD62Llo)." (PMID 39253969, 2024). "A significant statistical difference was found between COVID-19 patients and the control group regarding the frequency of CXCR2 rs2230054 C>T genotypes (P = 0.038)." (PMID 38544825, 2024).
COVID-19 (continued). "TNF-α, IL-8 and IL-10 are key cytokines in COVID-19 pathogenesis, and CXCR-2 is a major chemokine receptor involved in inflammatory response." (PMID 38544825, 2024). "CXCR2 was the only marker downregulated in whole blood neutrophils of patients with both mild and severe COVID-19." (PMID 39253969, 2024). "Increased transcriptional upregulation of the chemokine CXCR2 in the blood of patients with severe COVID-19 is also suggestive of MC precursor migration into lung, as was seen in the context of other diseases." (PMID 37561585, 2023). "Our results are in line with other studies that have identified both CD10low CXCR2high neutrophil subsets in severe COVID-19 by RNA sequencing and reduced CXCR2 expression in moderately ill patients." (PMID 36622345, 2023). "In contrast to CD10 expression, which was reduced on all neutrophils from COVID-19 patients, we detected severity-specific differences in CXCR2 expression." (PMID 36622345, 2023). "Frequencies of CXCR2+ cells were elevated on naïve, CM, and TM subpopulations in COVID-19 compared to healthy controls." (PMID 37946732, 2023). "These four inflammatory markers were mainly expressed by neutrophils, which have a high expression of the CXCL8 receptors CXCR1 and CXCR2, which showed a significant increase in both KD and severe COVID-19 when compared with the respective controls." (PMID 36159873, 2022). "The frequency of CD56dimCD16+ NK cells expressing solely CXCR2 was significantly reduced in COVID-19 patients." (PMID 35371005, 2022). "COVID-19 immune response and SZ share one DEG (activin A receptor type II-like 1, or ACVRL1) that is upregulated and two DEGs (CXCR2, CXCL1) that are both downregulated, all of which are strongly associated with the pathogenesis of COVID-19." (PMID 35185890, 2022). "In COVID-19 patients, CXCL1 binds to CXCR2 to promote immune cell chemotaxis, causing a cytokine storm that worsens the symptoms of patients." (PMID 35185890, 2022). "By day three to five post-admission, we report increased levels of senescent CXCR4+ CXCR2- neutrophils, confirming a report of reduced CXCR2+ neutrophils in ICU COVID-19 patients." (PMID 36139476, 2022). "Of note, in severe COVID-19 patients, lung tissue monocyte-derived macrophages may recruit neutrophils via the production of ligands for CXCR2." (PMID 40710346, 2025). "Furthermore, COVID-19 patients had a higher frequency of the polymorphic A allele of TNF-α, the A allele of IL-8, the G allele of IL-10, and the T allele of CXCR2." (PMID 38544825, 2024). "Interestingly, several studies have examined the clinical benefits of Navarixin (MK-7123/SCH 527123) and other CXCR2 inhibitors, a pharmacological intervention to block neutrophil recruitment to treat COVID-19." (PMID 38596679, 2024). "For example, we observed a decrease in the CXCR2+CXCR4–CD62L+ mature-homeostatic neutrophils and an increase in CD16+CD10+CXCR2+CXCR4+CD62L+ aged neutrophils in patients with COVID-19, indicating a potential link between these subpopulations and disease severity." (PMID 39253969, 2024). "The role of IL-8/CXCR2 signalling in disease progression is supported by whole blood RNA expression profiling (81Preprint) and an independent proteomic study, both of which report specific up-regulation of the pathway in severe COVID-19." (PMID 36622345, 2023). "In order to determine which subpopulations of CD8+ T cells might be responsive to MIF during COVID-19, the expression of CXCR2 and CXCR4 on CD74+ CD8+ T cells was analyzed." (PMID 37946732, 2023). "Down-regulation of CXCR2 in moderate COVID-19 may therefore be a protective, adaptive response that fails to occur in severe disease." (PMID 36622345, 2023). "Based on the findings in the current study, we strongly suggest the investigate of the use of CXCR2 antagonists in the treatment of severe COVID-19, which may exert beneficial effects on a systemic level, including a reducing in NETosis-induced thrombosis." (PMID 35420442, 2022).